IGF1 (insulin like growth factor 1)
Diseases named in the same sentence as IGF1 in open-access papers (continued):
Sharing a sentence is not in itself a finding about the gene and the disease.
Hypocalcemia (5 papers, 2013 to 2025). An abnormally decreased calcium concentration in the blood. "Four out of five males presented with primary hypogonadism, four out of five with mildly elevated prolactin, three out of seven with hypocalcemia, and five out of seven with elevated levels of insulin growth factor 1 (IGF-1)." (PMID 32575417, 2020). "Since several data in literature suggested a role of IGF-1 in muscle cells homeostasis, we asked whether extracellular hypocalcemia and hyperphosphatemia could alter this growth factor expression level." (PMID 37819413, 2024).
Hyponatremia (5 papers, 2010 to 2025). An abnormally decreased sodium concentration in the blood. "Taken together, decreased IGF-1 levels in skeletal muscles might be partly associated with diminished muscle strength induced by hyponatremia." (PMID 40227313, 2025). "The present findings suggest that IGF-1 might be related to muscle wasting and bone loss induced by hyponatremia in mice." (PMID 40227313, 2025). "In the present study, IGF-1 expression in muscle was decreased in mice with hyponatremia." (PMID 40227313, 2025). "She had hyponatraemia, elevated creatine phosphokinase, low thyroxine, prolactin, FSH, LH, and IGF-1." (PMID 33343948, 2020).
Immunodeficiency (5 papers, 2013 to 2026). Failure of the immune system to protect the body adequately from infection, due to the absence or insufficiency of some component process or substance. "A recent human study showed that a STAT5B gene mutation resulted in reduced serum IGF1 in most patients with immunodeficiency growth hormone insensitivity, accompanied by growth retardation and poor growth hormone therapy." (PMID 37235421, 2023). "Snell and Ames mice show early thymic involution and reduced primary immune responses, whereas Ghrh−/− mice, another model of severe GH and IGF-1 deficiency, do not present obvious immunodeficiency or thymic atrophy at least at 18 months of age." (PMID 41524828, 2026). "In non-pregnant adults, however, serum IGF1 has been shown to depend on level of immunodeficiency in HIV-infection and it was significantly higher in patients treated with protease inhibitors-based regimen compared to non-nucleoside reverse transcriptase inhibitors and healthy subjects." (PMID 31042729, 2019).
insomnia (5 papers, 2021 to 2025). A sleep disorder characterized by difficulty in falling asleep and/or remaining asleep. "Disruptions during sleep, such as insomnia, can affect GH and IGF-1 concentrations, because GH is preferentially released during slow-wave sleep." (PMID 37151979, 2023). "Our results appear to support the link between IGF-1 and insomnia and are in line with those of other studies on IGF-1." (PMID 37151979, 2023). "Further studies are needed to examine the relationship between IGF-1 and insomnia and their influence on accompanying symptoms." (PMID 37151979, 2023). "Among them, HP, MMP9, FGA, FGB, and FGG were validated as upregulated, and APP, AHSG, and IGF1 were downregulated in patients with insomnia." (PMID 35958162, 2022). "We hypothesized that patients with insomnia have a decreased serum IGF-1 concentration, which may play a role in the endocrine system, providing more evidence for the evaluation and treatment of insomnia." (PMID 37151979, 2023). "This indicates a potentially important role of IGF-1 in insomnia and emotional disorders." (PMID 37151979, 2023). "In the results, HP, FGA, FGG, FGB, and MMP9 were upregulated in patients with insomnia, and FN1, APP, EGF, AHSG, and IGF1 were downregulated compared with controls." (PMID 35958162, 2022). "The 10 key DEPs screened may be potential targets for insomnia, especially FN1, EGF, HP, and IGF1." (PMID 35958162, 2022).
Intraventricular hemorrhage (5 papers, 2021 to 2025). Bleeding into the ventricles of the brain. "A recent clinical trial indicated that supplementation with recombinant human (rh) IGF-1/rhIGF-binding protein 3 (rhIGF-1/rhIGFBP-3) prevents severe intraventricular hemorrhage (IVH) in extremely preterm infants." (PMID 34218224, 2021).
islet cell tumor (5 papers, 2008 to 2025). "The patient's laboratory results revealed low levels of IGF-1 (15 ng/ml), normal levels of IGF-2 (395 ng/ml), and an elevated IGF-2-to-IGF-1 ratio of 26:1, indicating non-islet cell tumor hypoglycemia." (PMID 39867043, 2024).
left ventricular hypertrophy (5 papers, 2009 to 2024). Enlargement of the LEFT VENTRICLE of the heart. "More frequent occurrence of left ventricular hypertrophy and deterioration of diastolic function in acromegalic patients may result from comorbidity and other factors like BMI and may not be directly related to elevated GH and IGF-1 values." (PMID 30123265, 2018).
leprosy (5 papers, 2011 to 2025). Leprosy is a chronic infectious disease affecting primarily the skin and peripheral nervous system. "The results of this study indicated that eye drops containing peptides derived from substance P and IGF-1 were effective in improving neurotrophic keratopathy in leprosy sequelae." (PMID 39717761, 2025).
mastitis (5 papers, 2010 to 2025). Inflammation of breast tissue during lactation or postpartum due to an obstructed duct or infection. "Insulin-like growth factor 1 (IGF-1) and its receptor have been identified as indicators of ketosis and are linked to an increased susceptibility to mastitis in dairy cows." (PMID 41139776, 2025). "MiR-183-5p via targeting BRCA1 may thus increase IGF-1 expression, which is in fact upregulated in the milk of cows suffering from mastitis." (PMID 36729355, 2023). "Notably, mastitis, a common inflammatory disease of lactating dairy cows, increases IGF-1 levels in milk whey." (PMID 36729355, 2023). "It is unclear how RASGRF1 associates with resistance/susceptibility to mastitis; however, previous work has shown that expression of RASGRF1 affects the function of the growth hormone-insulin-like growth factor 1 (GH-IGF-1) axis, which can modulate the inflammatory response to mastitis." (PMID 20942903, 2010). "It was reported that the concentration of IGF-1 and the numbers of SCC in milk of cows were greatly elevated in secretions of quarters affected by acute clinical as well as subclinical mastitis compared with the corresponding clinically healthy quarters." (PMID 25948480, 2015).
multinodular goiter (5 papers, 2014 to 2025). Nodular goiter characterized by more than one discrete tissue mass. "This characteristic supports the hypothesis that IGF-1 may regulate the thyroid growth and, therefore, may be involved in the pathogenesis of multinodular goiter." (PMID 30581552, 2018). "Intranodular IGF-1 and IGFBP-3 levels were significantly higher in the subjects with multinodular goiter compared to single nodules (p = 0.001 and p = 0.043, resp)." (PMID 29081797, 2017). "Our study demonstrated that the intranodular IGF-1 and IGFBP-3 levels were significantly higher in the subjects with multinodular goiter compared to single nodules." (PMID 29081797, 2017). "Intranodular IGF-1 and IGFBP-3 levels were significantly higher in subjects with multinodular goiter compared to the ones with single nodules." (PMID 29081797, 2017).
myoma (5 papers, 2014 to 2021). "For example, insulin and pioglitazone have been shown to have myoma inhibitory effects and IGF-1 levels decrease in treated diabetics." (PMID 25969688, 2015).
nephrotic syndrome (5 papers, 2017 to 2025). A collection of symptoms that include severe edema, proteinuria, and hypoalbuminemia; it is indicative of renal dysfunction. "In nephrotic syndrome, the levels of IGF-1 decrease, primarily due to the glomerular filtration of IGF-1-containing binding protein complexes." (PMID 39200324, 2024). "Taken together, in children with nephrotic syndrome IGF-1 levels are decreased and high-affinity IGFBPs (mainly IGFBP-1/-2) are markedly increased, resulting in an excess of unsaturated IGFBPs which may inhibit IGF action on target tissues by enhanced IGF-binding and/or competition with the IGF-1R." (PMID 34143299, 2021). "By use of micropuncture studies in rats with adriamycin-induced nephrotic syndrome, they could demonstrate that IGF-1 serum concentrations are markedly reduced and IGF-1 is highly ultrafiltrated together with IGFBP-2 appearing in proximal tubular fluid." (PMID 34143299, 2021).
pancreatic adenocarcinoma (5 papers, 2016 to 2023). "Insulin-like growth factor 1 (IGF-1) and insulin-like growth factor 2 binding protein (IGFBP2) are associated with an increased risk of cancer development, including pancreatic adenocarcinoma (PDAC)." (PMID 34830745, 2021).
parasite infection (5 papers, 2014 to 2024). "Recent studies further indicate that IGF-1, regulated by Ghrelin, may facilitate the progression of various parasitic diseases, potentially linked to improved immune inflammatory microenvironments that promote immune tolerance and evasion, thereby aiding parasite growth." (PMID 39749332, 2024). "While the mechanism of IGF1-mediated control of parasite infection was reasonably clear, our data suggested that the divergent effects of low and high IGF1 on A. stephensi survivorship and lifespan were more complex." (PMID 24968248, 2014). "Studies have reported that IGF-1 could accelerate the progression of parasitic infectious diseases." (PMID 39436864, 2024). "The termination of parasite infection restored the expression of these signaling proteins, which implies that the PI3-K and MAPK pathways participate in IGF-1 signaling to induce MMP-9 expression." (PMID 32972437, 2020).
Primary hypothyroidism (5 papers, 2010 to 2021). A type of hypothyroidism that results from a defect in the thyroid gland. "Primary hypothyroidism has also been described as a possible reason for significantly increased IGF‐1 concentrations." (PMID 34015193, 2021). "Similar to primary hypothyroidism, high total cholesterol and LDL levels, and low or low-normal levels of IGF-1 can be found in RTHα." (PMID 32349464, 2021).
protein deficiency (5 papers, 2013 to 2025). "Protein deficiency could decrease the secretion of insulin-like growth factor 1 (IGF-1), which may prevent normal growth of bone mass." (PMID 23914839, 2013).
protein-energy malnutrition (5 papers, 2005 to 2026). A nutritional deficit that is caused by inadequate protein or calorie intake. "IGF-1 has been shown to reduce in function with acute protein deficiency and in protein energy malnutrition in children." (PMID 39062266, 2024). "The serum IGF-1 levels decline in an age-dependent manner and are a reliable index of protein-energy malnutrition in elderly." (PMID 28900247, 2017). "Finally, among the blood values that are less likely to be measured routinely, IGF-1 is considered a useful parameter for early detection of protein-energy malnutrition." (PMID 34065864, 2021).
respiratory failure (5 papers, 2012 to 2024). The significant impairment of gas exchange within the lungs resulting in hypoxia, hypercarbia, or both, to the extent that organ tissue perfusion is severely compromised. "In animal models, mutations in the IGF-1 gene disrupt the architecture of lung tissue, leading to atelectatic lungs, respiratory failure, and high postnatal mortality." (PMID 39769074, 2024). "ROC analysis confirmed the prognostic accuracy of IGF-1 in discriminating between patients who experienced death/severe respiratory failure and those who did not (AUC 0.688, CI: 0.587 to 0.789, p < 0.001)." (PMID 36851702, 2023). "Similar to the poor survival and growth deficits in the Slc7a7-deficient mouse models, global Igf1−/− and Igf1r−/− mouse models with depleted circulating IGF-1 concentrations manifested early lethality (due to respiratory failure) and growth failure (27-60% of WT body weights)." (PMID 37486182, 2023).
scoliosis (5 papers, 2009 to 2025). A congenital or acquired spinal deformity characterized by lateral curvature of the spine. "In the longitudinal approach, while IGF-1 levels were low for all infants, they were even lower for those who later developed scoliosis." (PMID 34238321, 2021). "Although GH therapy has a good safety profile in girls with TS, close monitoring of IGF1 levels, abnormal glucose tolerance, reduced insulin sensitivity, benign intracranial hypertension, scoliosis and other skeletal changes at intervals of 3–6 months-is recommended." (PMID 34893062, 2021). "Tryptophan hydroxylase (TPH1 rs10488682), insulin-like growth factor (IGF1 rs5742612), neurotrophin 3 (NTF3 gene promoter at rs11063714), interleukin-17 receptor C (IL17RC rs708567), melatonin receptor 1B (MTNR1B rs4753426) were identified as risk factors for scoliosis curve progression." (PMID 39781499, 2025).
spinal cord injury (5 papers, 2016 to 2024). Penetrating and non-penetrating injuries to the spinal cord resulting from traumatic external forces (e.g., WOUNDS, GUNSHOT; WHIPLASH INJURIES; etc.). "The higher percentage of atrophy observed after spinal cord injury (SCI) compared to denervation has been related to the lower increase in IGF-1 expression and its receptor following SCI versus denervation." (PMID 37762414, 2023). "This study was conducted to investigate the effects of the exogenous overexpression of nerve growth factors NT-3 and IGF-1 on the recovery of nerve function after spinal cord injury (SCI) and identify the potential mechanism involved." (PMID 35573286, 2022).
Thrombocytopenia (5 papers, 2022 to 2024). A reduction in the number of circulating thrombocytes. "It is possible that at this stage platelets may have a more stimulating role in angiogenesis by releasing IGF-1, and that thrombocytopenia may cause an imbalance between the mediators of angiogenesis." (PMID 37129632, 2023). "Although it is not exactly understood how thrombocytopenia affects VEGF balance and phases of ROP, it is claimed that proliferative retinopathy occurs with an increase in endogenous production of IGF-1 by activation of retinal VEGF accumulation in ROP pathogenesis (second phase)." (PMID 35685577, 2022).
vascular dementia (5 papers, 2023 to 2025). A degenerative vascular disorder affecting the brain. "The progressive decline in IGF-1 levels experienced by the population is associated with impaired brain function and risk of vascular dementia." (PMID 37163437, 2023). "Third, decreased serum IGF-1—observed in individuals with lower weight—was identified as an independent risk factor for AD and vascular dementia." (PMID 36904288, 2023).
viral hepatitis (5 papers, 2014 to 2025). An acute or chronic inflammation of the liver parenchyma caused by viruses. "When compared to patients with viral hepatitis and healthy subjects, serum IGF-1 levels were significantly decreased in patients with HCC." (PMID 24586785, 2014). "Chronic viral hepatitis leads to reduction of IGF-1 and IGFBP-3 and an increase in GH secretion." (PMID 29449867, 2018). "Chronic viral hepatitis led to a reduction of IGF-1 and IGFBP-3 and increase in GH secretion." (PMID 29449867, 2018). "Results of the present study have consistently shown that the gradually decreased IGF-1 levels among healthy subjects, viral hepatitis patients and HCC patients were partially independent of AST, ALT and total bilirubin levels." (PMID 24586785, 2014). "Liver damage alone seems not to explain the greater decreases in IGF-1 levels of HCC patients compared with those of the viral hepatitis group." (PMID 24586785, 2014). "Besides, HCC and viral hepatitis groups showed significantly higher levels of AST, ALT and bilirubin than those of healthy controls, which supported that destruction of the liver parenchyma reduced serum IGF-1 levels." (PMID 24586785, 2014).
vitiligo (5 papers, 2021 to 2025). Generalized well circumscribed patches of leukoderma that are generally distributed over symmetric body locations and is due to autoimmune destruction of melanocytes. "Hence, a possible explanation for the vitiligo cell’s role is anomalous necessity of glucose to supply biological activity linked to Ins/IGF-1 stimulation and to rescue the related pro-mitogenic activity." (PMID 40277891, 2025). "In vitiligo keratinocytes, the intrinsic impairment of intracellular metabolic activities, particularly when associated with stimulation with Ins/IGF-1, converges into an aberrant pro-inflammatory phenotype that may initiate immune cell recruitment." (PMID 40277891, 2025). "Very recently, we provided evidence of Ins/IGF-1 resistance at the cellular level involving melanocytes, keratinocytes, and fibroblasts of vitiligo patients." (PMID 41007740, 2025). "Of note, prolonged exposition to IGF-1 and Ins, only in the vitiligo cells, resulted in toxic ROS production, exacerbating the inherent oxidative stress." (PMID 40277891, 2025). "In vitiligo cells, IGF-1 and insulin stimulation contributes to the aggravation of the energetic imbalance, a condition that promotes excessive glucose import responsible for nonenzymatic overproduction of advanced glycation end products (AGEs)." (PMID 41007740, 2025). "Hussein and collaborators recently reported lowered levels of IGF-1 in the skin and blood of vitiligo patients compared to reference samples, confirming the systemic nature of vitiligo." (PMID 40303919, 2025). "Correspondingly, the mitogenic and metabolic activities normally provoked by Ins/IGF-1 exposure resulted in significantly compromised vitiligo cells (p ≤ 0.05)." (PMID 40277891, 2025). "Further compounding this issue, El-Komy and colleagues reported significantly lower levels of IGF-1 in the serum and skin of vitiligo patients." (PMID 41007740, 2025). "Here, vitiligo cell growth in response to IGF-1 and Ins was assessed at concentrations routinely used for in vitro studies (0.01 μg/mL and 5 μg/mL, respectively)." (PMID 40277891, 2025). "Thus, we investigated the THP-1 differentiation profile in the presence of an IGF-1/Ins-conditioned secretome of the vitiligo keratinocytes." (PMID 40277891, 2025). "Furthermore, the intracellular level of ATP was faintly but constantly reduced by the addition of Ins and IGF-1 in vitiligo cells, indicating that the stimulation of receptors aggravates the intracellular energetic balance in the pathological context." (PMID 40277891, 2025). "There is also a growing understanding of the importance of insulin and IGF-1 signaling in vitiligo." (PMID 40303919, 2025). "Collectively, data support further exploration concerning IGF-1 supplementation to treat vitiligo." (PMID 40303919, 2025). "Thus, to verify if Ins and IGF-1 evoke a pro-inflammatory feature in vitiligo keratinocytes and the possible role in immunopathogenesis, we quantified the amount of several secreted interleukins that demonstrated increased quantities of CXCL10, IL-6, IL-8, IL-1α, IL1-β, and TNFα." (PMID 40277891, 2025). "Here, we provided evidence of Ins/IGF-1 resistance at the cellular level involving the dermal and epidermal non-lesional cells of vitiligo patients." (PMID 40277891, 2025). "Similarly, both the healthy and vitiligo keratinocytes failed to phosphorylate AKT under Ins/IGF-1 stimulation in a hyperglycemic condition." (PMID 40277891, 2025).
3M syndrome (4 papers, 2014 to 2024). 3M syndrome is a primordial growth disorder characterized by low birth weight, reduced birth length, severe postnatal growth restriction, a spectrum of minor anomalies (including facial dysmorphism) and normal intelligence. "Previous studies suggested a degree of GH resistance as well as GH deficiency being possibly related with the 3M syndrome, and it was also reported that the 3M syndrome may be associated with the dysregulations of GH, IGF1, and IGF binding proteins." (PMID 27796265, 2017).
airway hyperresponsiveness (4 papers, 2018 to 2024). "IGFBP-3 also reduces IGF-1 expression, and blockade of IGF-1 with an neutralizing antibody is also shown to inhibit ovalbumin-induced VEGF expression, airway inflammation, and airway hyperresponsiveness." (PMID 30018981, 2018).